FTH1 (ferritin heavy chain 1)
Diseases named in the same sentence as FTH1 in open-access papers (continued):
Sharing a sentence is not in itself a finding about the gene and the disease.
tumor (continued). "Conversely, in tumor tissues with low TSPO expression, AKR1C1 and FTH1 are similarly found to have low expression." (PMID 40842566, 2025). "Subsequent IHC analysis of GPX4, FTH1 and TFRC expression in subcutaneous tumours from DLBCL xenograft model yielded similarly results." (PMID 40038872, 2025). "NCOA4 and FTH1 are involved in iron metabolism and ferroptosis, with NCOA4 acting as a tumor suppressor and FTH1 promoting tumor progression." (PMID 40649942, 2025). "Conversely, the genes FTH1, SQSTM1, HSPA6, TSPYL2, PHLDA2, ITGAX, and DNAJA4 are expected to act as versatile protein regulators, potentially suppressing tumor cell genetic instability and promoting autophagy, apoptosis, and other forms of cell death." (PMID 40986633, 2025). "Compared with the pcDNA3.1-NC group, increased TRAIL reduced the expression of FTH1, GPX4, and SLC7A11 in tumor tissues (P < 0.01)." (PMID 38383815, 2024). "Previous studies have reported that increased FTH1 and FTL1 expression inhibited ferroptosis in tumor cells." (PMID 39857341, 2024). "Here, we observed a direct correlation between FTH1 expression and cell viability and clonogenicity in KRAS-mutant PDAC cell lines as well as with in vivo tumor growth through the control of proline metabolism." (PMID 39294443, 2024). "BECN1, ELAVL1, and ATG16L1 were highly expressed in tumor tissues, while NCOA4, FTH1, FTL, SNCA, TNF, ATG7, and ZFP36 showed low expression levels." (PMID 39593730, 2024). "The basal tumor cells of cSCC samples in our study highly expressed CCL2, CXCL14, FTH1, MT2A, which is consistent with the findings in Tumor_KC_Basal." (PMID 38099574, 2023). "PEO1 tumor spheroids, instead, maintain approximately unaltered CD71, reduce FPN while further strongly increase FtH1." (PMID 38033861, 2023). "In the clinical group Tumor status: Tumor free and with tumor, the genes TOP2A, BIRC5, VEGFA had highly statistical significance, while the genes HIF1A, ACSL3, FTH1 didn’t have statistical significance." (PMID 37248280, 2023). "Based on FTH1 and FTL1, the coding genes for the heavy chain and light chain of ferritin significantly highly expressed in tumor samples from HNSCC patients, and we further analyzed their clinical prognostic value." (PMID 38025726, 2023). "The expression of all six FRGs was significantly different (p < 0.05), with FTH1, FTL, and PCBP1 being overexpressed in the tumor group and ZFP36, NCOA4, and TNF expressed less in the tumor group." (PMID 37555866, 2023). "PRMT9 knockdown also significantly suppressed FTH1 protein expression and enhanced MDA content in HCC tumor tissues." (PMID 37715221, 2023). "At the same time, immunohistochemistry showed that the expression of FTH1, FTL in tumor tissues was significantly higher than that in para-tumor tissues." (PMID 37555866, 2023). "We here develop a novel cancer therapy named Ferroptosis ASsassinates Tumor (FAST) by combining iron oxide nanoparticles with cancer-selective knockdown of seven key ferroptosis-resistant genes (FPN, LCN2, FTH1, FSP1, GPX4, SLC7A11, NRF2)." (PMID 36329436, 2022). "In this study, TmSm was fused to the C‐terminus of the FTH1 gene via an MMP‐2‐sensitive peptide (P‐L‐G‐L‐A‐G), which is responsive to the tumor microenvironment for site‐specific release of the TmSm protein." (PMID 35600646, 2022). "The expression profile of TRFC, FTH1, and FTL is positively correlated with tumor pathological grade and affects tumor progression like renal cell carcinoma, head and neck squamous cell carcinoma, and breast cancer." (PMID 35126346, 2021).
tumor (continued). "In the present study, we found that expressions of FTL and FTH1 correlated positively with levels of the immune checkpoint proteins TIM-3 and LAIR1, both of which can suppress tumor immunity." (PMID 33864445, 2021). "Interestingly, high intracellular iron and FTH1 suppressed cell surface expression of major histocompatibility complex (MHC) class 1 on tumor cells and macrophages and consequently, iron depletion rendered tumor cells highly susceptible to death by natural killer (NK) cells." (PMID 32328462, 2020). "Additionally, FTL and FTH1 bind the anti-angiogenic molecule high molecular weight kininogen (HKa), preventing its dimerization, necessary for its functional activity and consequently, promoting endothelial cell survival, migration, adhesion, and angiogenesis to support tumor growth." (PMID 32328462, 2020). "Consistently, an increase in the expression levels of GPX4 and FTH1 observed in in Tumor#1 compared to Para#1 but not in Tumor#2 compared to Para#2." (PMID 39540244, 2025). "The observed alterations in iron regulation, including increased FTH1 and decreased NCOA4, point to a shift in iron storage capacity that may contribute to immunosuppression in the tumor microenvironment." (PMID 40765825, 2025). "Additionally, western blotting validates the expression of FTH1, GPX4, SLC7A11, FSP1 and DHODH in fresh surgical tumour tissues from three imatinib‐resistant patients compared with three imatinib‐sensitive patients receiving neoadjuvant imatinib therapy." (PMID 40866937, 2025). "Besides, Nrf2 regulates ferroptosis in tumor cells by inducing the expression of NQO1, HMOX1, and FTH1." (PMID 40530331, 2025). "have demonstrated that PCIF1, an RNA N6 2′‐O‐dimethyladenosine (m6Am) methyltransferase, can reduce the m6Am modification on ferroptosis suppressor genes such as FTH1, SLC3A2 and T‐cell activation marker CD69 in CD8+ T cells, which further promotes CD8+ T‐cell ferroptosis and enhances tumour growth." (PMID 40045458, 2025). "We investigated the immunolabeling of TfR1, TfR2, and FTH1 in SCO tubules within different microenvironments (immersed in SEMs, immersed in SCTs, or isolated from tumor cells) to provide insights into the possible role of SCO tubules as precancerous testicular conditions." (PMID 40427255, 2025). "Among the fourteen ferritinophagy-related genes studied, ten exhibited significant differences between tumor and normal samples: NCOA4, FTH1, FTL, SNCA (all p < 0.0001), BECN1 (p = 0.031), ELAVL1 (p = 0.00023), TNF (p = 0.00074), ATG16L1, ATG7, and ZFP36 (all p < 0.0001)." (PMID 39593730, 2024). "Furthermore, the JAK-STAT signaling pathway was enriched in the low FTH1 expression groups of ESCA and LUSC, emphasizing FTH1’s role in multiple immune activities and its potential indispensable function in the anti-tumor immune process." (PMID 38281198, 2024). "The SUIT-2 xenograft tumor volume was significantly lower with FTH1 knockdown (284 ± 47 mm3) than without FTH1 knockdown (970 ± 119 mm3 for SUIT-2 cells and 1007 ± 129 mm3 for the Scr group) and with rescued FTH1 expression (431 ± 44 mm3)." (PMID 39294443, 2024). "It is necessary to explore whether NEDD4L could suppress tumor progression via targeting other ferroptosis core genes, such as GPX4, ASCL4 and FTH1." (PMID 39557844, 2024). "Interestingly, decreased TfR1 expression and increased FTH1 expression were observed in the ITSEM germ cells, suggesting the presence of a second iron uptake pathway in this type of tumor, which should be further investigated in future studies." (PMID 39272404, 2024). "Likewise, LASS2 overexpression reversed the changes in the levels of FTH1, FTL and GPX4 induced by either Fer-1 or erastin in these tumour cell lines." (PMID 38419028, 2024). "Although the source of SF is unclear, several studies have suggested that secreted ferritin contains both heavy (FTH1) and light (FTL) ferritin chain subunits, and its subunit composition in tumor ferritins may vary among different cancers." (PMID 39294443, 2024).
tumor (continued). "In addition, PB can also suppresses tumor growth in an orthotopic mouse model of GC via regulating the expression of GPx4, TFR1, NOCA4 and FTH1 in vivo." (PMID 36923926, 2023). "FtH1 knockdown significantly reduces the generation of PEO1 tumor spheroids, although without sensitizing them to ferroptosis." (PMID 38033861, 2023). "The extent of “iron-addicted phenotype” is determined by the innate expression pattern of iron regulatory proteins (i.e., CD71, FtH1, and FPN) and by the relative innate intracellular iron levels, and ultimately affects the sensitivity of tumor cells to ferroptosis." (PMID 38033861, 2023). "Similarly, compared to that in peritumor tissues, the expression of ferroptosis-inducing genes, including PTGS2, HMOX1, TFR2, and NCOA4, was down-regulated in tumor tissues, whereas ferroptosis-suppressor genes SLC7A11 and FTH1 were upregulated." (PMID 37554285, 2023). "It's worth noting that genes associated with metal ion regulation, including zinc regulators MT1 and MT2, which have been reported to be enriched in dysfunctional CD8 + tumor-infiltrating T cells, and iron regulators SLC40A1 and FTH1, were also found to be involved in this process." (PMID 37957625, 2023). "When grown in the culture medium supplied with iron, FtH1 silencing remarkably diminishes the number of tumor spheroids (from 1,228 to 958, *p-value <0.05) without affecting their size." (PMID 38033861, 2023). "Importantly, tumoral c-Jun expression was positively correlated with SOX9, SOX2, OCT4, FTH1, FTL and TFRC expression in consecutive PDAC tumour tissues." (PMID 37143164, 2023). "To this, we performed the transient knockdown of FtH1 and upon 4 days we observed a reduction of FtH1 gene expression of about 70% in PEO1 tumor spheroids grown both in iron-rich and non-iron rich culture media." (PMID 38033861, 2023). "Moreover, the fluorescence intensity of tumors treated with the FTS/cyanine NCs was significantly higher than that of those treated with FTH1/cyanine NCs and free cyanine, suggesting that FTS/cyanine NCs had a better tumor‐targeting effect." (PMID 35600646, 2022). "The average tumor size at Day 12 in the FTS/YM155 NC group was 331.7 ± 54.0 mm3, while it was 583.7 ± 91.6, 992.7 ± 154.5, 814.8 ± 141.0, and 1226.6 ± 216.5 mm3 in the FTS NC + YM155, FTH1/YM155 NC, FTS NC, and TmSm treatment groups, respectively." (PMID 35600646, 2022). "Here, we developed MMP‐2‐sensitive FTH1 NCs—specifically TmSm‐modified FTH1 NCs carrying YM155 (FTS/YM155 NCs)—for the codelivery of YM155 and TmSm to synergistically inhibit survivin activity at both the transcript and protein levels at a tumor‐specific site." (PMID 35600646, 2022). "The reduction in the expression levels of NRF2, GPX4, HO-1, and FTH1 by caryophyllene oxide also inhibited GSH and hydroxyl radical’s inhibitory capacities in serum, and promoted iron deposition in tumor tissue resulting in the inhibition of tumor growth." (PMID 35899120, 2022). "We speculate that FTL and FTH1 may influence TIM-3 and LAIR levels by affecting immune cell infiltration into the tumor." (PMID 33864445, 2021). "IRP2 was decreased in tumours, a normal response to high intracellular iron, but this did not lead to a reduction in TfR1 or an increase in FTH1 as expected." (PMID 34211054, 2021). "A notable exception was FTH1, whose levels were >15-fold higher in NCU samples, suggesting it was associated with cells, although not necessarily tumor cells, as it was present in comparable quantities in both healthy control and BPH urine samples." (PMID 32098402, 2020). "Upregulation of FTH1, ferritin heavy chain 1, may be a compensatory response to C3’s effects on angiogenic pathways, as FTH1 can reestablish tumor angiogenesis." (PMID 29464047, 2018). "IL1RN inhibits PGE2, IL-6 production and MM cell growth, FTH1 is a favorable prognostic protein but is not really known to contribute to anti-tumor response and the death receptor FAS induces apoptosis in a large number of cell types." (PMID 26036313, 2015).
tumor (continued). "Firstly, the PEG3 promoter is activated specifically in tumor cells by the PEA3/AP-1 transcription factors, regulating the specific expression of FTH1 at the transcriptional level, thereby ensuring FTH1 expression is restricted to tumor tissues and absent in normal tissues." (PMID 40723232, 2025). "Furthermore, the increased expression of RGS5,a regulator of vascular maturation, and FTH1,involved in iron metabolism, implies a supportive role for EC5 cells in maintaining endothelial integrity and remodeling the tumor microenvironment to favor metastatic colonization." (PMID 41394809, 2025). "Our results indicate that SUIT-2 cells subjected to FTH1 silencing exhibit a significant decrease in PYCR1 mRNA and protein levels, whereas those with induced FTH1 overexpression demonstrate a restoration of PYCR1 expression and a corresponding impact on tumor growth." (PMID 39294443, 2024). "Notably, some of these genes, including FTH1 and SLCO2A1, play pivotal roles in tumour progression." (PMID 39393173, 2024). "Furthermore, bioinformatics analyses using publicly available gene expression datasets revealed upregulation of both FTH1 and NUPR1 mRNA expression in HCC tumor groups compared to normal groups, with a significant positive correlation between NUPR1 and FTH1 mRNA expressions in these HCC datasets." (PMID 38802795, 2024). "In comparison to the control group, the ferroptosis-related proteins COX2, NRF2, and CD71 were upregulated, and GPX4, xCT, FTH1, and FLCA were downregulated dose-dependently in the uridine-treated group, indicating that uridine could inhibit HCC tumor growth in vivo via the induction of ferroptosis." (PMID 37240659, 2023). "However, the role played by ferritin in regulating the tumor microenvironment is unclear, and little is known about whether or how FTL and FTH1 expression levels might correlate with tumor infiltration by diverse immune cell subsets." (PMID 33864445, 2021). "Additionally, BCa tissues with high levels of FTH1 tend to be highly enriched for interferon gamma‐producing CD8+, but not CD4+, T cells, suggesting that FTH1 modulates the adaptive immune response within the tumor microenvironment." (PMID 34551213, 2021). "However, the mechanism by which FTH1 exerts its possible tumor suppressor effects in BCa is not known." (PMID 34551213, 2021). "Furthermore, six tumor progression genes (GNAI2, ODC1, APP, TNFRSF12A, BASP1, and LARP6) and nine migration and metastasis‐related genes (MSN, FLOT1, LAMB3, MYL9, ITGB1, FTH1, TPM4, and PMEPA1), which could explain the invasive characteristics of SCC, were identified." (PMID 40776410, 2025). "Also, FTH1‐DOX had been shown to have a longer plasma half‐life and higher area under the concentration time curve, which might improve the retention of the drug in the systemic circulation and promote the time‐dependent accumulation of the drug in the tumor." (PMID 35600646, 2022). "We observed that VPA effectively blocked the transcription of FTL, FTH1 and NQO1 in tumor tissues, with or without Erastin treatment, and DFS treatment didn't affect the function of VPA." (PMID 40963919, 2025).
cancer (128 papers, 2012 to 2026). A tumor composed of atypical neoplastic, often pleomorphic cells that invade other tissues. "Altered metabolism is a hallmark of cancer; thus, we further investigated FTH1-mediated metabolic reprogramming in pancreatic cancer." (PMID 39294443, 2024). "A comprehensive analysis of the association between FTH1 levels and immunotherapy responses across various cancers is warranted to enhance our understanding of the impact of ferroptosis on immunotherapy." (PMID 38281198, 2024). "The results reveal that the expression of FTH1 in cancer was elevated compared to adjacent tissues and FTH1 overexpression indicated a higher risk of lymph node metastasis and poor prognosis of patients with HNSCC." (PMID 38025726, 2023). "As was observed for OS, poor PFI was significantly associated with high FTL or high FTH1 mRNA levels in some cancers." (PMID 33864445, 2021). "Nevertheless, the silencing of FTH1 in human erythroleukemia blast cells affects their erythroid fate underlining the role of FTH in cancer cell differentiation." (PMID 34831207, 2021). "FTH1 has been linked to drug resistance in breast and ovarian cancer wherein downregulation of FTH1 increased chemosensitivity." (PMID 32328462, 2020). "Cluster 4 contained only 3 transcripts, composed of ferritin light chain (FLT) and ferritin heavy chain (FTH1), which have been associated with several cancers." (PMID 28957348, 2017). "Moreover, our analyses revealed positive associations between FTL and FTH1 expressions and infiltration of both cell types in most cancers." (PMID 33864445, 2021). "In-silico analysis also revealed miR-3613-3p’s potential to target FTH1, a gene involved in iron homeostasis and oxidative stress regulation in cancer cells, making it a key therapeutic candidate." (PMID 41378310, 2025). "While FTH1 can protect healthy cells from hypoxia damage, cancer cells, on the other hand, can use the same mechanism to their advantage in sustaining and activating tumorigenesis." (PMID 39852175, 2025). "In particular, gene expression of TMBIM6, AP2M1, and PTP4A2 (correlated with cancer progression and cell cycle) increased, while levels of FTH1 (coding for the ferritin heavy chain) were decreased." (PMID 40076697, 2025). "Another important co-expression pair comprised FAM99B and FTH1, pointing to a potential involvement in iron homeostasis and oxidative stress response, both of which are altered in cancer cells." (PMID 40248203, 2025). "To investigate the relationship between TSPO and ferroptosis in MPNST, we used RT-qPCR to detect the differential mRNA expression levels of two classic ferroptosis biomarkers, AKR1C1 and FTH1, in tissues from patients with benign and malignant tumors." (PMID 40842566, 2025). "All these findings highlight a strong correlation between FTH1, cancer cells, and immune cells in TIME." (PMID 38281198, 2024). "Subsequently, cell-cell communication analysis indicated that HMOX1+macrophages had the most interactions with cancer cells, while FTH1+macrophages had the fewest." (PMID 39238647, 2024). "We evaluated the impact of aberrant FTH1 mRNA expression on various cancers using the Kaplan–Meier plotter." (PMID 38281198, 2024). "The suppression of FTH1 not only impaired cancer cell viability but also appeared to sensitize the cells to DFX treatment, thus enhancing the efficacy of the drug." (PMID 39294443, 2024). "FTH1 inhibits the accumulation of intracellular Fe2+ and reduces cancer cell sensitivity to ferroptosis." (PMID 38802795, 2024). "FTH1 exhibited aberrant expression patterns across multiple cancers, which is strongly correlated with immunotherapy resistance." (PMID 38281198, 2024). "The downregulation of piR-FTH1 has been demonstrated to target FTH1 mRNA, thereby promoting the chemosensitivity of cancer cells." (PMID 39795985, 2024). "To investigate deeply the underlying mechanisms involved in the function of FTH1, we conducted KEGG GSEA across 33 human cancers." (PMID 38281198, 2024).